LINC00538 (long independently transcribed non-coding RNA 538)
Synonyms: Yiya; PROX1UT
Gene: Long non-coding RNA gene on chromosome 1 (213,924,749 to 213,926,654, reverse strand). Ensembl gene ENSG00000281664.
Diseases named in the same sentence as LINC00538 in open-access papers:
LINC00538 is named in the same sentence as 4 diseases in open-access papers, as found by Europe PMC text mining. Sharing a sentence is not in itself a finding about the gene and the disease. The quoted sentences say what the papers report.
colorectal cancer (1 paper, 2018). A primary or metastatic malignant neoplasm that affects the colon or rectum. "Growth arrest specific 5 (GAS5) and LINC00538 (Yiya) are promising prognostic biomarkers for liver metastases in patients with early-stage colorectal cancer." (PMID 29784063, 2018).
cancer (1 paper, 2020). A tumor composed of atypical neoplastic, often pleomorphic cells that invade other tissues. "Glucose transporters (GLUTs) as important modulators of glucose utilization which are commonly dysregulated in cancer, have been shown to be targeted by several lncRNAs such as LINC01638, Ftx, XIST, YIYA (LINC00538), HISLA, AWPPH, and UCA1." (PMID 33123468, 2020).
tumour (1 paper, 2021). "Similarly, deletion of LINC00538 (YIYA) in human breast cancer strongly inhibited the tumour growth and invasion in vitro and suppressed tumour growth in a mouse xenograft model." (PMID 34072257, 2021).
LINC00538 also shares sentences with these, for which no sentence is quoted: breast carcinoma (3 papers).